CELF1 (CUGBP Elav-like family member 1)
Description:
RNA-binding protein implicated in the regulation of several post-transcriptional events. Involved in pre-mRNA alternative splicing, mRNA translation and stability. Mediates exon inclusion and/or exclusion in pre-mRNA that are subject to tissue-specific and developmentally regulated alternative splicing. Specifically activates exon 5 inclusion of cardiac isoforms of TNNT2 during heart remodeling at the juvenile to adult transition. Acts both as an activator and as a repressor of a pair of coregulated exons: promotes inclusion of the smooth muscle (SM) exon but exclusion of the non-muscle (NM) exon in actinin pre-mRNAs. Activates SM exon 5 inclusion by antagonizing the repressive effect of PTB. Promotes exclusion of exon 11 of the INSR pre-mRNA. Inhibits, together with HNRNPH1, insulin receptor (IR) pre-mRNA exon 11 inclusion in myoblast. Increases translation and controls the choice of translation initiation codon of CEBPB mRNA. Increases mRNA translation of CEBPB in aging liver (By similarity). Increases translation of CDKN1A mRNA by antagonizing the repressive effect of CALR3. Mediates rapid cytoplasmic mRNA deadenylation. Recruits the deadenylase PARN to the poly(A) tail of EDEN-containing mRNAs to promote their deadenylation. Required for completion of spermatogenesis (By similarity). Binds to (CUG)n triplet repeats in the 3'-UTR of transcripts such as DMPK and to Bruno response elements (BREs). Binds to muscle-specific splicing enhancer (MSE) intronic sites flanking the alternative exon 5 of TNNT2 pre-mRNA. Binds to AU-rich sequences (AREs or EDEN-like) localized in the 3'-UTR of JUN and FOS mRNAs. Binds to the IR RNA. Binds to the 5'-region of CDKN1A and CEBPB mRNAs. Binds with the 5'-region of CEBPB mRNA in aging liver. May be a specific regulator of miRNA biogenesis. Binds to primary microRNA pri-MIR140 and, with CELF2, negatively regulates the processing to mature miRNA.
Synonyms: BRUNOL2; CUGBP; CUGBP1; NAB50; CUG-BP; hNab50; NAPOR; EDEN-BP
Tractability: PROTAC: UniProt records ubiquitination sites on it; ubiquitination databases record sites on it; its protein half-life has been measured.
Gene: Protein-coding gene on chromosome 11 (47,465,933 to 47,565,569, reverse strand). Ensembl gene ENSG00000149187.
Subcellular location: Nucleus; Cytoplasm
Subcellular location (Human Protein Atlas): Nucleoplasm
Gene Ontology:
Molecular function: BRE binding; mRNA 3'-UTR binding; mRNA binding; pre-mRNA binding; protein binding; RNA binding; mRNA regulatory element binding translation repressor activity; nucleic acid binding
Biological process: mRNA splice site recognition; negative regulation of gene expression; positive regulation of gene expression; post-transcriptional gene silencing; regulation of inflammatory response; regulation of RNA splicing; embryo development ending in birth or egg hatching; germ cell development; mRNA destabilization; mRNA processing; negative regulation of cell population proliferation; regulation of alternative mRNA splicing, via spliceosome; regulatory ncRNA-mediated post-transcriptional gene silencing; negative regulation of translation
Cellular component: cytoplasmic stress granule; membrane; nucleoplasm; nucleus; perinucleolar compartment; ribonucleoprotein complex; cytoplasm
Genetic constraint (gnomAD): Loss-of-function variants: 7 observed, 53.2 expected, observed/expected ratio (o/e) 0.13, 90% interval 0.074 to 0.25. The upper end of that interval is the gene's LOEUF score, 0.25, which puts it in group 1 of 6, group 1 being the genes least tolerant of losing a copy. Missense variants: 342 observed, 602.81 expected, observed/expected ratio (o/e) 0.57, 90% interval 0.52 to 0.62. Synonymous variants: 224 observed, 220.38 expected, observed/expected ratio (o/e) 1.02, 90% interval 0.91 to 1.13.
Homologues: Orthologues: chimpanzee CELF1 (100% identical), macaque CELF1 (99% identical), mouse Celf1 (99% identical), rat Celf1 (99% identical), dog CELF1 (99% identical), pig CELF1 (99% identical), rabbit CELF1 (98% identical), guinea pig CELF1 (95% identical), tropical clawed frog celf1 (90% identical), zebrafish celf1 (82% identical), Drosophila melanogaster bru2 (51% identical), Drosophila melanogaster bru1 (47% identical), and 4 more. Paralogues in human: CELF2 (76% identical), CELF5 (45% identical), CELF3 (44% identical), CELF4 (44% identical), CELF6 (43% identical), RBM28 (21% identical).
Diseases named in the same sentence as CELF1 in open-access papers:
CELF1 is named in the same sentence as 87 diseases in open-access papers, as found by Europe PMC text mining. Sharing a sentence is not in itself a finding about the gene and the disease. The quoted sentences say what the papers report.
myotonic dystrophy type 1 (24 papers, 2011 to 2025). Steinert disease, also known as myotonic dystrophy type 1, is a muscle disease characterized by myotonia and by multiorgan damage that combines various degrees of muscle weakness, arrhythmia and/or cardiac conduction disorders, cataract, endocrine damage, sleep disorders and baldness. "Up-regulation of CELF1 in the adult heart contributes to the pathogenic reiteration of fetal splicing patterns in myotonic dystrophy type 1 (DM1) mouse models and human patients." (PMID 26866591, 2016). "CELF1 levels peak in the heart during embryogenesis, and aberrant up-regulation of CELF1 in the adult heart has been implicated in cardiac pathogenesis in myotonic dystrophy type 1, as well as in diabetic cardiomyopathy." (PMID 26866591, 2016). "CELF1, primarily acknowledged as a vital regulator in the development of myotonic dystrophy type 1 (DM1) disease, has now been associated with liver dysfunction and specific cancer types, highlighting its multifaceted roles." (PMID 41306913, 2025). "CELF1 has been reported to play a role in myotonic dystrophy type 1 (DM1), a type of muscular dystrophy in humans, via interactions with the dystrophia myotonica-protein kinase (DMPK) gene." (PMID 39858630, 2025). "While CELF1 has been best characterized in the context of myotonic dystrophy type 1 (DM1) models, a growing body of work has associated CELF1 overexpression with cancer proliferation, migration, invasion, and overall tumor aggressivity in multiple cancer models." (PMID 39343007, 2024). "CELF1, also referred to as CUG-binding protein 1 (CUGBP1), is found mostly in the heart, skeletal muscle, and brain, and has been linked to myotonic dystrophy type 1, muscle wasting, and Alzheimer’s disease, as well as multiple cancers." (PMID 34681716, 2021). "Hyperphosphorylation of CELF1 has been reported as a major contributor to pathogenesis in myotonic dystrophies, such as myotonic dystrophy type 1 (DM1)." (PMID 26821046, 2016). "CELF1 is primarily studied for its contributory role in myotonic dystrophy type 1 (DM1) disease progression however, recent emerging evidences support CELF1 as a potential regulator of cancer progression." (PMID 26498364, 2015). "CELF1 gene may have a role in myotonic dystrophy type 1 (DM1) because of its interactions with the dystrophia myotonica-protein kinase (DMPK) gene." (PMID 29056900, 2017). "The CELF1 gene may play a role in myotonic dystrophy type 1 (DM1) via interactions with the dystrophia myotonica-protein kinase (DMPK) gene." (PMID 24237593, 2013). "The aberrant expression of CELF1 leads to multiple diseases such as myotonic dystrophy type 1 (DM1), myocardial hypertrophy." (PMID 38443798, 2024). "Cardiac conduction defects decrease life expectancy in myotonic dystrophy type 1 (DM1), a CTG repeat disorder involving misbalance between two RNA binding factors, MBNL1 and CELF1." (PMID 31829940, 2019). "This variant was predicted by SnpEff to be a modifier and is an intron of CUGBP Elav-like family member 1 (CELF1), a gene suspected to be involved in myotonic dystrophy type 1." (PMID 31637255, 2019). "In patients with myotonic dystrophy type 1 (DM1), an adult-onset form of muscular dystrophy caused by the expression of mutant transcripts from the DMPK gene containing expanded CUG repeats, CELF1 is aberrantly up-regulated in the heart and skeletal muscles." (PMID 21541285, 2011). "Steinert disease, or myotonic dystrophy type 1 (DM1), is a multisystemic disorder caused by toxic noncoding CUG repeat transcripts, leading to altered levels of two RNA binding factors, MBNL1 and CELF1." (PMID 29716962, 2018). "In patients with myotonic dystrophy type 1 (DM1), dysregulation of RNA-binding proteins like MBNL and CELF1 leads to alternative splicing of exons and is thought to induce a return to fetal splicing patterns in adult tissues, including the central nervous system (CNS)." (PMID 35274098, 2022).
myotonic dystrophy (17 papers, 2009 to 2025). An inherited progressive disorder affecting the muscles. "Celf1 deficiency in mouse causes spermatogenesis defects and its mis-regulation is associated with myotonic dystrophy in human." (PMID 29565969, 2018). "Celf1 has a role in cells as different as sperm, muscle, and lens cells, among others, and its alterations are associated with various types of cancer and developmental defects including heart defects, myotonic dystrophy and cataracts." (PMID 37048143, 2023). "hnRNPA1 is also abnormally expressed in myotonic dystrophy, where similar to CELF1, it promotes fetal splicing patterns and antagonizes MBNL activity." (PMID 34685485, 2021). "Most well-studied RBPs in muscle are associated with or causal for muscle diseases, notably CELF1 and MBNL1 (myotonic dystrophy), SMN (spinal muscular atrophy), TDP-43, and Rbm20 and Rbm24 (dilated cardiomyopathy)." (PMID 34685485, 2021). "Such regulation is also disease relevant, as for example CUG repeat expansions found in patients with myotonic dystrophy sequester MBNL1 resulting in the abnormal stabilization of CELF1, disrupting normal RBP function." (PMID 34685485, 2021). "CELF1 is upregulated in heart and skeletal muscle in myotonic dystrophy (DM) patients, disruption of CELF1-mediated alternative splicing is linked to DM symptoms." (PMID 31534127, 2019). "Among them CUGBP1, so called CELF1 (CUGBP Elav-like family member 1), is reported to be overexpressed in DM (Myotonic dystrophy) and several cancer cells." (PMID 29036189, 2017). "Nevertheless, our findings are consistent with a recent study, which suggested that DMPK is implicated in myotonic dystrophy by its dysregulation of MBNL1 and CELF1 mediated alternative splicing of the L-type calcium channel CACNA1S." (PMID 28152551, 2017). "Studies have shown that CELF1 is primarily found in skeletal muscle, heart, and brain, initially discovered to be involved in the selective translation of muscle atrophy kinase in myotonic dystrophy." (PMID 40781108, 2025). "CELF1 has been reported to promote transcript deadenylation and the abnormal up-regulation of its protein level could contribute to the myotonic dystrophy pathology." (PMID 31425505, 2019). "One implication is that altered function of CELF1 in myotonic dystrophy may contribute to changes in the extracellular matrix of affected muscle through defects in secretion." (PMID 28129347, 2017). "This preferential expression of CELF1 over MBNL1, which mirrors that of the myotonic dystrophy model, most likely triggers the abnormal splicing of L-type calcium channels resulting in the reduced contractility in the Srf KO smooth muscle." (PMID 28152551, 2017).
breast carcinoma (14 papers, 2013 to 2025). "Cox and random-forest analyses prioritized CELF1 among prognosis-related RBPs in luminal A tumors; high CELF1 associated with poorer survival and was overexpressed in breast cancer versus normal tissue." (PMID 41306913, 2025). "This insight into the interplay between CELF1 and the insulin receptor sheds light on potential mechanisms underlying breast cancer progression and offers avenues for further research into targeted therapies." (PMID 38443798, 2024). "Within multiple in vitro experimental systems, CELF1 protein expression is both necessary and sufficient to drive EMT, and CELF1 loss-of-function in mesenchymal/de-differentiated breast cancer cell lines drives them back to a more epithelial/differentiated state." (PMID 39343007, 2024). "Our results define and genetically order an 11-member post-transcriptional regulatory circuit underlying breast cancer progression in which CELF1 (CUG RNA-binding protein and embryonically lethal abnormal vision-type RNA-binding protein 3-like factor 1) functions as a central regulator." (PMID 27869122, 2016). "We hypothesized that CELF1 misexpression might be an underlying feature of human breast cancer." (PMID 27869122, 2016). "Diverging from preceding investigations, our research employed a varied array of molecular subtypes of cell lines and breast cancer tissues, leading us to discern the impact of CELF1 on apoptosis and cell cycling progress." (PMID 41306913, 2025). "Subsequently, we reduced CELF1 levels in luminal breast cancer cells and enhanced CELF1 expression in HER2-positive breast cancer cells using shRNA and the pcDNA3.1-CELF1 plasmid, respectively." (PMID 41306913, 2025). "Our research has led us to uncover a set of genes enriched in breast cancer influenced by CELF1, which shows distinctive prognostic value specifically in luminal A breast cancer." (PMID 41306913, 2025). "Our findings confirmed that CELF1 promotes the aggressiveness of breast cancer cells, which was supported by both in vitro and in vivo experiments." (PMID 41306913, 2025). "Our data suggest that CELF1 is expressed and functional in different molecular subtypes of breast cancer; additionally, CELF1 drives the metabolic preference for aerobic glycolysis in breast carcinomas by modulating the expression of GLUT1." (PMID 41306913, 2025). "In our analysis of the UALCAN platform, we observed a significant overexpression of CELF1 in luminal breast cancer, while its expression was comparatively lower in the HER2-positive subtype." (PMID 41306913, 2025). "We highlighted CELF1 as a potentially key regulator of metabolic reprogramming in luminal A breast cancer, thereby shedding light on new directions for future research and treatment strategies." (PMID 41306913, 2025). "In the context of this study, we observed that CELF1 is expressed and functional across diverse molecular subgroups of breast cancer; additionally, by modulating the expression of GLUT1, CELF1 stimulates aerobic glycolysis in breast cancer cells." (PMID 41306913, 2025). "In particular, the luminal A-type breast cancer patients with low CELF1 expression had a median survival time of 216.2 months." (PMID 41306913, 2025). "To further investigate this, we compared CELF1 mRNA levels in different molecular subtypes of breast cancer tissues, including normal breast tissues, luminal, HER2+, and TNBC samples using RT-PCR." (PMID 41306913, 2025). "Collectively, these results suggest that the role of CELF1 levels differs according to the specific molecular subtype of breast cancer." (PMID 41306913, 2025). "For a more comprehensive understanding of how CELF1 functions in breast cancer, we performed RNA sequencing (RNA-seq) analysis on both CELF1-KO MCF7 cells and wild-type MCF7 cells." (PMID 41306913, 2025). "We subsequently revealed the importance of RNA-binding protein CELF1 in luminal A subtype breast cancer." (PMID 41306913, 2025).
breast carcinoma (continued). "Here we established that CELF1 phosphorylation is an event conserved in two distinct breast cancer cell lines and used our primary model system to identify the sites phosphorylated on CELF1 within this context." (PMID 39343007, 2024). "As an RNA binding protein, overexpression of CELF1 has been associated with many diseases, for example, CELF1-OE was correlated with lower levels of endogenous p27, at the same time, repressing p27 IRES activity in human breast cancer cell line MCF7." (PMID 35287612, 2022). "In breast cancer, CELF1 promotes exon 11 exclusion of the INSR (insulin receptor gene), promoting the production of the pro-tumorigenic IR-A splicing isoform." (PMID 34681716, 2021). "CELF1 protein was reported to be significantly overexpressed in human breast cancer tissues by functioning as a central node controlling translational activation of genes driving EMT and tumor progression." (PMID 29728583, 2018). "We evaluated CELF1 expression in two human breast cancer arrays, together comprising 140 distinct breast cancers and 76 normal adjacent tissue controls." (PMID 27869122, 2016). "We examined TCGA transcriptional data sets representing 111 cases of human breast cancer and paired normal tissues for changes in the relative expression of the CELF1 mRNA and its regulatory targets." (PMID 27869122, 2016). "We next correlated relative CELF1 protein expression with a number of different breast cancer patient variables." (PMID 27869122, 2016). "We evaluated whether CUGBP Elav-like family member 1 (CELF1), an RBPs with prognostic relevance in luminal A (ER-positive) breast cancer, drives malignant phenotypes via glycolytic reprogramming through glucose transporter 1 (GLUT1)." (PMID 41306913, 2025). "Therefore, further exploration is warranted to elucidate the interplay between CELF1 and ER in breast cancer." (PMID 41306913, 2025). "Among RBPs in luminal breast cancer, CELF1 emerged as a leading contributing factor." (PMID 41306913, 2025). "The functional role of CELF1 was assessed in breast cancer cells." (PMID 41306913, 2025). "Additionally, when examining CELF1 expression in breast cancer cells at both transcriptional and protein levels, we observed a pronounced upregulation specifically in luminal breast cancer cells, as opposed to HER2-positive cells." (PMID 41306913, 2025). "CELF1 immunoprecipitated from this cell line was similarly phosphorylated on serine and threonine (but not tyrosine) residues, consistent with the notion that CELF1 stabilization by phosphorylation in breast cancer cell lines is evolutionarily conserved." (PMID 39343007, 2024). "Additionally, it has been observed that insulin stimulation enhances the carcinogenic regulatory effects of CELF1 in breast cancer cells." (PMID 38443798, 2024). "Given the broad dysregulation of CELF1 expression in human breast cancer, our results may ultimately provide knowledge that may be leveraged for novel therapeutic interventions in this context." (PMID 39343007, 2024). "Moreover, lowering CELF1 is the main mechanism of tumor suppression of breast cancer cells with a combination of glycyrrhetinic acid and doxorubicin." (PMID 34681716, 2021). "Recent studies report that CELF1 regulates the translation of ten drivers of epithelial to mesenchymal transition (EMT), CELF1 is significantly overexpressed in human breast cancer tissues and is necessary and sufficient for both EMT and metastatic colonization." (PMID 31534127, 2019). "Under the rationale that CELF1 gene expression might be similarly regulated in the context of human breast cancer, we next asked whether dysregulation of CELF1 protein expression in breast cancer might be visualized via immunohistochemistry." (PMID 27869122, 2016).